CD4 (CD4 molecule)
Diseases named in the same sentence as CD4 in open-access papers (continued):
Sharing a sentence is not in itself a finding about the gene and the disease.
dengue (continued). "The use of immunoinformatics tools to design a multi-epitope vaccine construct based on CD4+ epitopes identified from the DENV-1 proteome is a promising strategy for the development of an effective dengue vaccine." (PMID 37987878, 2023). "CD4+ cytotoxic T cells have been identified as responsible for liver dysfunction in dengue fever, involving mechanisms such as bystander lysis." (PMID 37234451, 2023). "Some authors have indicated that a Th1 CD4+ profile is protective against dengue, while a shift to Th2 is involved in disease severity." (PMID 38003826, 2023). "After a secondary infection, progression to uncomplicated dengue featured transcriptional profiles associated with increased cell proliferation and metabolism, and an expansion of ICOS+CD4+ and CD8+ effector memory T cells." (PMID 37055751, 2023). "In this study, we aimed to characterize circulating EVs from different categories of dengue patients and examined the consequence of naïve CD4+ T cells to EVs isolated from the plasma of mild or severe dengue patients." (PMID 37982662, 2023). "In contrast to PBS plus alum injected control mice, DSV4 immunized mice had a higher frequency of TH1 CD4+ T cells on stimulation with dengue EDIII 1-4 peptide pool." (PMID 36926350, 2023). "Treatment of purified naïve CD4+ T cells with EVs derived from severe dengue plasma drove CD4+ proliferation toward specific subtypes and modulated surface receptor CXCR3 and CCR6 expression." (PMID 37982662, 2023). "Our data show that DSV4 immunization in mice leads to the development of not only IFN-γ-producing T cells but also dengue EDIII-specific TFH CD4+ T cells and polyfunctional TH1 cells." (PMID 36926350, 2023). "T CD4+ regulatory cells control the production of vasoactive cytokines after dengue stimulation, and a high ratio of T regulatory cells/effector T cells is associated with mild disease." (PMID 38003826, 2023). "In conclusion, the use of immunoinformatics tools to explore the dengue (DENV-1) proteome and design a multi-epitope vaccine construct by using CD4+ epitopes is a promising approach to develop an effective dengue vaccine." (PMID 37987878, 2023). "CD38, Plasma cells, activated memory CD4+ T cells and Monocytes can be used to distinguish clinical stages for dengue patients, and ZNF595 can be used to discriminate DHF from DF, regardless of serotypes." (PMID 35918744, 2022). "Although a recent study revealed that CD4+ CTLs show marked clonal expansion heterogeneously across individuals with dengue virus infection, thus far, the role of CD4+ CTLs during Mtb infection has not been fully understood." (PMID 35197957, 2022). "Plasma cells (AUC = 0.968), activated memory CD4 + T cells (AUC = 0.845) and Monocytes (AUC = 0.869) can excellently distinguish Dengue samples from normal samples in GSE51808." (PMID 35918744, 2022). "First, the report that the frequency of a novel CD4+CD8+ DP T cell subset was increased in D+L versus D-L, and it is thus associated with risk of plasma leakage in dengue disease." (PMID 35062294, 2022). "In contrast, high levels of CD4+ cells were found in severe and fatal dengue cases, even with increased numbers of CD8+ T cells in patients with DHF." (PMID 35372587, 2022). "Our results suggest that immune response to dengue is dysregulated with predominance of CD4+ T cells, low activation of Th1 cells, and downregulation of the antiviral cytotoxic activity during severe dengue, likely induced by regulatory T cells." (PMID 35372587, 2022). "CD38 and Plasma cells have excellent Area Under the Curve (AUC) in distinguishing clinical stages for Dengue patients, and activated memory CD4+ T cells and Monocytes have good AUC for this function." (PMID 35918744, 2022). "To further investigate the role of CD4+CD8+ DP T cells in the pathogenesis of plasma leakage in dengue, we compared transcriptomic profiles between the D+L and D-L groups during the acute febrile phase." (PMID 35062294, 2022).
dengue (continued). "In line with these protective roles, CD4 CTLs were also detected in patients affected by Dengue, a mosquito-borne viral disease that has rapidly spread in recent years." (PMID 35572552, 2022). "CD4+ T lymphocytes, including cytotoxic CD4+ T cells, in turn, seem to play important role in protection against severe dengue development." (PMID 35047911, 2021). "Although the protection of rMV-TDV against DENV-2 infection evidenced by reduced viremia and no inflammatory cytokine increase was encouraging, the immunodominant DENV-3 CD4+ T-cell responses induced by the tetravalent dengue vaccine attracted more attention." (PMID 32300346, 2020). "Our results also showed a decline in total CD4+ T, Th1, Th1/17 cells during febrile phase of dengue patients compared to normal controls or convalescent phase." (PMID 33072068, 2020). "The activated CD4+ T cells will then provide help to CD8+ T cells that are then able to directly kill dengue infected cells through recognition a variety of dengue proteins including the non-structural NS3 and NS1.2a proteins." (PMID 32655548, 2020). "Our data demonstrate that most treated HIV patients diagnosed with acute dengue disease had lower CD4 absolute counts and inverted CD4/CD8 T- cell ratio." (PMID 32286360, 2020). "Despite these caveats, the more consistent and broad nAb and CD4+ T-cell responses induced by EDIII + PP highlights the potential of combining our approach with antigen optimization in dengue and other vaccine development." (PMID 31285858, 2019). "As seen in other studies, DENV-specific T cell frequencies ex vivo in dengue-resolved infections are low, particularly for CD4+ T cells." (PMID 30327651, 2018). "Dot plots are shown for one representative dengue-immune and dengue-naive donor and results for all donors are summarized for CD4+ and CD8+ T cells (n = 10, n = 14)." (PMID 30327651, 2018). "Our data show that, despite the overall low levels of IFN-γ production in T cells of dengue-immune individuals, CD4+ and CD8+ T cell recognition of ZIKV NS3 protein was present and comparable to that of DENV NS3." (PMID 30327651, 2018). "Future studies will address the secretion of multiple cytokines and marker expression revealing potential additional dengue-specific CD4+ T cell responses but also specific polarizations of T cell responses between the different cohorts." (PMID 29081779, 2017). "The number of CD4+ T cell lymphocytes, located primarily within the renal glomerulus, was also found to be increased in dengue group renal sections, when compared to controls." (PMID 28006034, 2016). "Our findings shed light on how ED3-based tetravalent dengue vaccines sharpen host CD4 T-cell responses and contribute to protection against dengue virus." (PMID 26714037, 2015). "We found that cooperation between CD4+ T cells and the humoral response plays a critical role on the protection against dengue mediated by the NS1 antigen." (PMID 26650916, 2015). "Successful development of a safe and efficient tetravalent dengue vaccine will be aided by the systematically analysis of CD4+ T-cell responses." (PMID 26714037, 2015). "To address this issue, we focus on the ED3, which is the major target site for neutralizing antibodies, to characterize the ED3-specific CD4+ T-cell responses elicited by tetravalent dengue vaccines." (PMID 26714037, 2015). "Previous studies to identify CD4+ T-cell responses were performed on the subjects infected with dengue, mostly for DENV-2 and analyzed at a genome-wide scale." (PMID 26714037, 2015). "Our data indicate that CCR5+ cell rates present among all CD4 T cells as well as among all CD8 T cells were markedly higher during dengue disease as compared to controls." (PMID 22815692, 2012). "We had observed high prevalences of herpes viruses, dengue and hepatitis B virus in the study area, and had seen specific CD4+ T cell responses against Plasmodium falciparum in 14 out of 17 healthy adults in Nouna (data not shown)." (PMID 22177276, 2011).
dengue (continued). "During primary infections in mice, dengue specific CD4+ cells were low; however, in all four viral serotypes of a secondary infection there is a marked increase CD4+ response." (PMID 19941667, 2009). "There is a differential cytokine secretion in response to antigen exposure in CD4+ cells in Dengue infected donors." (PMID 19941667, 2009). "Therefore, we conducted a study to understand the effect of dengue plasma-derived EV and EV-modulated CD4+ Tcell interaction on ECs." (PMID 39745465, 2025). "Since CD8+ T cells have been shown to play an important role in viral clearance during primary dengue while CD4+ T cells were dispensable, a CD8+ T-cell depletion experiment was conducted to further evaluate the role of this cell subset during infection with WT or T209L DENV mutant." (PMID 40962941, 2025). "Using EA.hy926 cells and HUVEC cells, we have demonstrated that (i) severe dengue plasma-derived EV (SD-EV)-treated CD4+ T cells have retarded proliferation and impaired the migratory ability of endothelial cell (EC); (ii) SD-EV-CD4+ T cell induces PD-L1 expression on endothelial cells." (PMID 39745465, 2025). "Finally, another component of the immune response that seemed to be involved in the pathogenesis of dengue is the participation of CD4+ regulatory T cells, Treg cells, during the infectious process." (PMID 40299497, 2025). "Recent studies have identified highly polarized CX3CR1+ cytotoxic CD4+ T cells in dengue patients, which exhibit potent antiviral activity and could serve as targets for novel vaccine strategies." (PMID 40431664, 2025). "In summary, the comprehensive compendium of the dengue-specific CD4 and CD8 T cell peptide epitopes provided here will serve as a fundamental foundation and resource for future efforts aimed at evaluating, assessing and comprehending dengue-specific CD4 and CD8 T cell responses." (PMID 38793612, 2024). "Our present study highlights that EVs from plasma of severe dengue patients can have immunosuppressive properties on CD4+ T cells which may contribute to T cell suppression and may contribute to dengue disease progression." (PMID 37982662, 2023). "Dengue virus infection results in generation of both CD4+ and CD8+ dengue‐specific TRM." (PMID 37144705, 2023). "However, the percentage of CD4+ T cell suppression was significantly reduced in PD-L1 antibody-treated EVs isolated from severe dengue plasma, suggesting that EV-induced CD4+ suppression was mediated through PD-L1-PD1 interaction." (PMID 37982662, 2023). "Thus, IL-2 secretion is crucial in dengue-infected patients for the differentiation of naïve CD4+ T cells into regulatory CD4+/CD25high/Foxp3+ T cells." (PMID 38003826, 2023). "Regulatory T cells (Tregs) are another population of CD4 T cells which could expand in acute dengue to suppress highly cross-reactive DENV-specific T cells contributing to disease pathogenesis." (PMID 35215836, 2022). "Interestingly, we found that the fraction of Plasma cells, activated memory CD4+ T cells and Monocytes in Dengue patients also had clinical characteristics and can distinguish these clinical stages for Dengue patients." (PMID 35918744, 2022). "Therefore, we can discriminate three stages based on the fraction of Plasma cells, activated memory CD4 + T cells and Monocytes in Dengue patients." (PMID 35918744, 2022). "In particular, comprehensive epitope identification studies have revealed that CD4+ and CD8+ T cell responses restricted to HLA molecules associated with a “low risk” of severe dengue display more robust and polyfunctional responses than cells restricted to “high-susceptibility” HLA molecules." (PMID 31244855, 2019). "Both NME1 and IFIT3 were expressed by CD4+ T cells from dengue-infected patients." (PMID 31624246, 2019). "We first investigated the extent of cross-reactive T cell recognition of ZIKV antigens by dengue-specific memory T cells and asked whether cross-reactivity could be detected in both CD4+ and CD8+ T cell compartments." (PMID 30327651, 2018).
dengue (continued). "Therefore, a significant advancement in the Dengue vaccine field would be the development of a safe, sub-unit vaccine that can generate Dengue specific neutralizing antibodies, CD4+ T cells and CD8+ T cell responses." (PMID 27703172, 2016). "Interestingly, there was a significant increased proportion of CD4 T cells expressing CD107a in all dengue status and still in convalescent group as compared to healthy individuals." (PMID 22815692, 2012). "The CD107a expression was found on CD4+ T cells in addition to CD8+ during dengue fever, an observation that fits with cytotoxicity reports from anti-dengue CD4+ T-cell lines, indicating that this cell population might play an important in vivo cytotoxic role." (PMID 22815692, 2012). "Interestingly, CD4+ T cell responses appear to vary with dengue disease severity." (PMID 40469309, 2025). "We provided evidence that SD-EV induces PD-1 and CD44 on CD4+ T cells and, when interacting with endothelial cells (EC), drives endothelial damage through direct interaction or secretome and may be significant in dengue-mediated endothelial dysfunction." (PMID 39745465, 2025). "Thus, whereas CD16+ NK cells and non-classical monocytes appear to be associated with progression to severe dengue, TH1-polarised TFH cells and ICOShigh CD4+ and CD8+ effector memory T cells are features associated with more favourable infection outcomes after a secondary DENV infection." (PMID 37055751, 2023). "In humans, we and others have shown that in acute infection, DENV-specific CD4+ T cells are not characterized by changes in phenotype or functional attributes, arguing against the notion that altered CD4+ T-cell phenotype or function may be a determinant of severe dengue disease." (PMID 35455361, 2022). "Previous studies also indicated that CD4+ EMRA cells could demonstrate cytotoxic features and express the chemokine receptor CX3CR1 in the setting of Dengue virus infection, which are associated with cytotoxic lymphocytes with cytoplasmic granules containing perforin and granzymes." (PMID 35287794, 2022). "Dengue virus (DENV)-specific CD4 T cells had direct ex vivo cytolytic activity and were enriched in patients carrying HLA histocompatibility alleles associated with disease protection, suggesting that DENV-specific CD4 CTLs may directly contribute to the control of severe dengue pathology in vivo." (PMID 35572552, 2022). "In addition, DENV-specific CD4 T cells with cytotoxic activity have been reported by numerous studies and their frequency may be lower in patients with more severe dengue disease." (PMID 31552052, 2019). "An hypothesis about the pathogenesis of DHF, though proven true in vivo, involves immune clearance by way of induction of cross-reactive T-cell memory, T-cell proliferation, and recognition of dengue viral antigens on infected monocytes by sensitized CD4+CD8– and CD4–CD8+ cytotoxic T cells." (PMID 16494756, 2006). "Progress in these directions is critically dependent on a detailed understanding of dengue-specific CD8 and CD4 T cell epitopes conserved among circulating dengue viruses and determining which of these are shared by vaccine candidates." (PMID 38793612, 2024). "For example, we have shown that asymptomatic infected patients show an increased activation of the CD4+ and CD8+ T-cell compartment compared to hospitalized dengue patients." (PMID 38752787, 2024). "Our initial step involved a compilation of experimentally validated CD4 T cell epitopes and CD8 T cell epitopes specific to dengue, as sourced from the literature, across various global regions." (PMID 38793612, 2024). "This dengue EDIII-specific IFN-γ T cell response was seen equally among both CD4+ and CD8+ T cells, showing that dengue EDIII can serve as an epitope for both CD4+ and CD8+ T cells." (PMID 36926350, 2023).
dengue (continued). "On evaluating the cytokine function of the TFH CD4+ T cells in DSV4 immunized mice, we found that dengue EDIII 1-4 peptide pool stimulation resulted in a significantly higher proportion of IL-21+ and IL-10+ TFH CD4+ T cells." (PMID 36926350, 2023). "In our study, all effector memory CD4+ and CD8+ T cell subsets found in individuals progressing to uncomplicated dengue expressed high level of co-stimulatory molecules, including ICOS." (PMID 37055751, 2023). "In line with our findings, previous reports of our group regarding dengue fatal cases of adults also revealed an increase in CD8+T and CD4+T cell subpopulations in liver tissues." (PMID 37457689, 2023). "CD4+ and CD8+ T cells from dengue-infected patients stimulated with envelope and NS3 dengue antigens produce multifunctional T cells secreting IFN-γ, TNF-α, and IL-10." (PMID 38003826, 2023). "Between mild and severe dengue groups, PD-L1 expression significantly enhanced in SDV-EVs, suggesting that MDV-EV- and SDV-EV-treated CD4+ T cells are exhausted T cells and thus probably less responsive to proliferation." (PMID 37982662, 2023). "Both CD4+ and CD8+ T cells were stimulated with dengue EDIII 1-4 peptide pool secreted higher amounts of IFN-γ in DSV4 immunized mice compared to PBS control mice." (PMID 36926350, 2023). "On the other hand, both absolute CD4 and CD8 counts were significantly increased in dengue patients with the febrile phase." (PMID 35782108, 2022). "Multifunctional CD4+ T cells (predominantly expressing IL-2) were induced by DPIV, with higher frequencies in dengue-primed adults." (PMID 36316335, 2022). "B-cell epitopes and dengue-specific CD8+ and CD4+ lymphocytes are not only involved in pathogenesis and immunological research but also are main targets for vaccine and diagnostic reagent development against dengue virus." (PMID 36430387, 2022). "Another dengue live attenuated tetravalent vaccine (DLAV) was developed very recently and it showed a rapid increase of IFNg+TNF-α+-producing CD4+ T cells and then CD8+ T cells within 8–14 days after vaccination." (PMID 35215836, 2022). "Our results agree with the observation that human CD4+ CTLs are enriched in the CD4+ T EMRA subset, most notably in donors with previous infection of dengue or cytomegalovirus." (PMID 34386013, 2021). "Dengue-infected DCs present the antigen to CD8+ and CD4+ T cells in the T-cell zones of the draining LN, where the adaptive immune response begins." (PMID 32655548, 2020). "Notably, however, in vitro infection with dengue led to a significant increase in frequency of CD4+ T cells and subsets of T cells—which was not noted in response to Zika infection—likely reflecting experience with that virus (e.g., Treg, Th2, and CD4+ Teff and CD8+ Teff cells)." (PMID 32150565, 2020). "Furthermore, previous studies have reported that cross-reactive peptide sequences led dengue-exposed subjects to develop stronger anti-Zika CD4 and CD8 T cells responses, suggesting that exposure to dengue infection may in fact augment cellular immune responses to infection with Zika." (PMID 32150565, 2020). "The role of both conventional CD4+ and CD8+ T cells in dengue has been well studied and show they are highly activated, and recent investigations have shown that T cells in dengue are likely to have a protective role." (PMID 32264870, 2020). "It seems that the distribution of CD4+ T-cell epitopes varied between different serotypes of DENV but shifted to the conserved/cross-reactive CD4+ T-cell epitopes following multiple rounds of DENV infection, as seen in dengue-specific CD8+ T cells." (PMID 32300346, 2020). "In summary, our data show that CD4+ and CD8+ T cells from 70% of individuals with prior dengue immunity are able to recognize peptides from ZIKV NS3 protein." (PMID 30327651, 2018).